ENSG00000281159
Gene: Small Cajal body-specific RNA gene on chromosome 2 (130,929,762 to 130,929,883, reverse strand). Ensembl gene ENSG00000281159.
Gene Ontology:
Biological process: RNA processing
Cellular component: Cajal body; nucleolus
Homologues: Orthologues: mouse Gm25820 (82% identical). Paralogues in human: SCARNA15 (50% identical).